AFP (alpha fetoprotein)
Diseases named in the same sentence as AFP in open-access papers (continued):
Sharing a sentence is not in itself a finding about the gene and the disease.
germ cell tumor (continued). "Thus, such markers are used frequently in clinical practice as for example, CEA (Carcinoembryonic antigen) in colon tumors, CA19-9 (Carbohydrate antigen 19-9) in pancreatic cancer and a combination of AFP (Alpha-fetoprotein) and HCG (Human chorionic gonadotropin) in testicular germ-cell tumors." (PMID 37810977, 2023). "Moreover, the combination of a typical tumorous lesion of the pineal region and the laboratory findings of elevated alpha fetoprotein (AFP) and beta human choriogonadotropin (β-HCG) in either serum or cerebrospinal fluid establishes the diagnosis of a secreting germ cell tumor." (PMID 32504201, 2021). "AFP is a known marker for nonseminomatous germ cell tumors, and its expression may point at development of endodermal component within our observed formations." (PMID 34831039, 2021). "The OCT-3/4, CD30 and AFP are not specific markers of germ cell tumors." (PMID 25815097, 2014). "GTS refers to a rapidly growing pure mature (benign) teratoma that appears during or following chemotherapeutic eradication of malignant components of a nonseminomatous germ cell tumor, and it has normal serum tumor marker levels of alpha-fetoprotein and human chorionic gonadotropin." (PMID 23762690, 2013). "Additionally, seminomas, a type of TGCT, do not produce AFP, so an elevated AFP level would not be indicative of a seminoma but could suggest the presence of non-seminomatous germ cell tumors (NSGCTs)." (PMID 38611057, 2024). "Tumor marker testing, encompassing alpha-fetoprotein (AFP) (with consideration for age-dependent values) and beta-human chorionic gonadotropin (beta-hCG) in both blood and cerebrospinal fluid (CSF), proves invaluable in diagnosing nongerminomatous germ cell tumors." (PMID 38610689, 2024). "Furthermore, the SUVmax could differentiate between seminomas and nonseminomatous germ cell tumors (p = 0.042) and reflect serum alpha fetoprotein (AFP) levels (p = 0.012)." (PMID 37848723, 2023). "However, the serum AFP level could not distinguish pregnant patients with germ cell tumors (p = 0.077)." (PMID 36556136, 2022). "Although P3 had moderately elevated AFP noted at BL, CT and histology confirmed classical TCS stage 1 without invasion and “no suggestion of non-semanomatous germ cell tumour (NSGCT)”." (PMID 39934683, 2025). "AFP and HCG serve as significant biomarkers, with approximately two-thirds of patients experiencing recurrent non-seminomatous germ cell tumors exhibiting elevated marker levels." (PMID 40308496, 2025). "ITs are also generally negative at the immunochemistry evaluation for AFP, OCT4, CD30, and PLAP, which are markers more typical of other germ cell tumor components." (PMID 41008884, 2025). "Alpha-fetoprotein (AFP) and beta-human chorionic gonadotropin (β-hCG) serve primarily as surveillance markers for recurrent germ cell tumors (e.g., teratomas), rather than for initial diagnosis." (PMID 41341341, 2025). "In this patient, AFP and β-HCG levels were normal, a finding that is characteristic of metastatic testicular involvement from SCLC rather than primary germ-cell tumors, which typically produce elevated markers." (PMID 41583290, 2025). "Laboratory findings, particularly elevated AFP and LDH levels, were consistent with the diagnosis of non-seminomatous germ cell tumors." (PMID 39171067, 2024). "Immunohistochemical staining showed positivity for steroidogenic factor 1 (SF1), calretinin, inhibin, and in sporadic cells, for AFP, while staining for SALL4, which is known to be a malignant germ cell tumor marker, was negative." (PMID 39336518, 2024). "The American Children’s Oncology Group CNS Nongerminomatous Germ Cell Tumor Phase II Trial (ACNS1123) sets HCG at 100 IU/L and AFP at 10 ng/mL, while the European SIOP GCT II Trial sets HCG at 50 IU/L and AFP at 25 ng/mL." (PMID 38790424, 2024). "Negative reactivity for CD30, CD117, AFP, OCT4, and PLAP argues forcefully against the diagnosis of most germ cell tumors." (PMID 37189109, 2023).
germ cell tumor (continued). "However, the patient had a significantly increased level of AFP, and 18F-FDG PET/CT showed the retroperitoneal metastasis had increased FDG uptake, with a SUVmax of 15.6, suggesting the coexistence of other germ cell tumor components, and the patient might have a poor prognosis." (PMID 37731724, 2023). "The current biomarkers alpha-fetoprotein (AFP) and human chorionic gonadotropin (HCG) have limited sensitivity/specificity for diagnosing malignant germ cell tumors (GCTs) and “marker-negative” patients require histological confirmation for diagnosis." (PMID 32642701, 2020). "These markers are not very specific; AFP and HCG are increased in 50-70% and in 40-60% of patients with non-seminomatous germ cell tumors, respectively, whereas HCG elevation can be detected in only 30% of seminomas." (PMID 31851466, 2020). "AFP-producing clear cell type EOC has two characteristics: an ovarian clear cell carcinoma with and without typical germ cell tumor." (PMID 29933751, 2018). "In men, however, tests for prostate-specific antigen (PSA), serum chorionic gonadotropin (β-hCG), and alpha-fetoprotein (AFP) are recommended, to rule out treatable extragonadal germ cell tumours or prostate cancer eligible for endocrine therapy." (PMID 29808414, 2018). "AFP and β-HCG are primarily elevated in specific components of non-seminomatous germ cell tumors." (PMID 40241724, 2025). "In seminomas, the elevated levels of AFP, β-HCG, and LDH are observed in 2.8%, 28%, and 29.1% of cases, respectively, whereas in non-seminomatous germ cell tumors, the elevated levels of these biomarkers are found in 60.1%, 53.0%, and 38.7% of cases, respectively." (PMID 40241724, 2025). "Alpha-fetoprotein (AFP), β-human chorionic gonadotrophin (β-HCG), and lactate dehydrogenase (LDH) levels were within normal ranges, and the diagnosis was stage IB nonseminomatous germ cell tumor." (PMID 38898921, 2024). "In addition, immunohistochemical analysis of AFP, Sal-like protein 4 (SALL4), PLAP, c-kit, and D2-40, performed to differentiate chordoma from lung metastases of germ-cell tumors, were all negative." (PMID 38961474, 2024). "While serum tumor markers (AFP and ß-HCG) play an important role at the time of first diagnosis to correctly classify prognosis and treatment of germ cell tumors, they may not have the same significance in a late relapse situation." (PMID 34518930, 2022). "In our case, germ cell tumors including yolk sac and embryonal carcinoma were the most possible differentials which were excluded by the negative IHC results for SALL4, CD30, Glypican 3 and AFP (alpha-fetoprotein)." (PMID 35797874, 2022). "Before undergoing any procedure, including orchiectomy, serum tumor markers like AFP, human chorionic gonadotropin, and LDH should be tested since they may be raised in non-seminomatous testicular germ cell tumors." (PMID 36627995, 2022). "Although AFP is not specific for HCC, elevated AFP levels are seen in chronic liver disease, especially viral hepatitis, and non-hepatic malignancies such as pancreatic, gastric, biliary and germ cell tumors." (PMID 25128299, 2014).
gastric cancer (187 papers, 2004 to 2026). A primary or metastatic malignant neoplasm involving the stomach. "Alpha‐fetoprotein (AFP)‐producing gastric cancer (AFPGC) is resistant to chemotherapy and is associated with poor prognosis." (PMID 40922714, 2025). "AFP is primarily utilized for hepatocellular carcinoma diagnosis but is also expressed in certain cases of gastric cancer, a pattern associated with specific molecular pathological alterations and prognostic implications, warranting further investigation." (PMID 40406247, 2025). "Alpha‐fetoprotein (AFP)‐producing gastric cancer (AFPGC) is associated with chemotherapy resistance and poor prognosis." (PMID 40922714, 2025). "Transcriptome sequencing studies have indicated that genes highly expressed in AFP-producing gastric cancer are associated with the activation of various oncogenic pathways, whereas genes with low expression are often involved in immune responses." (PMID 40430002, 2025). "This study aimed to retrospectively analyze the diagnostic and prognostic value of CA125, CEA, and AFP individually and in combination for gastric cancer, thereby providing additional clinical insights for the diagnosis and treatment of gastric cancer." (PMID 40406247, 2025). "Elevated AFP levels in gastric cancer patients have been associated with poor differentiation, advanced disease stage, and shortened overall survival." (PMID 40299527, 2025). "A potential biological mechanism underlying elevated AFP levels in gastric cancer involves hepatic differentiation or hepatocellular-like differentiation of gastric tumor cells." (PMID 40485723, 2025). "AFP is typically elevated only in a distinct subset of gastric cancers (the AFP-producing variant) known for aggressive behavior." (PMID 40299527, 2025). "Previous studies found that elevated AFP level in gastric cancer was a risk factor for postoperative liver metastasis, which were consistent with our findings." (PMID 40900791, 2025). "AFP-producing gastric carcinomas, including GACED, are frequently associated with conventional adenocarcinomas, including papillary and tubular adenocarcinoma." (PMID 41041100, 2025). "In conclusion, our result showed that gastric cancer with high serum AFP level was associated with a poor prognosis and a high incidence of liver metastasis." (PMID 38355790, 2024). "Beyond HCC, AFP production is observed in gastric cancer (GC), specifically AFP-producing gastric carcinoma (AFPGC), associated with higher metastatic risk and poorer prognosis." (PMID 39135041, 2024). "In conclusion, gastric cancer is associated with age, gender, and the positive levels of AFP, CEA, CA125, CA199, and CA242." (PMID 35611170, 2022). "Our research shows that gastric cancer is associated with age, gender, and the positive levels of AFP, CEA, CA125, CA199, and CA242." (PMID 35611170, 2022). "Although AFP-producing gastric cancer (AFP-GC) is a rare subtype of gastric cancer, it is associated with a high incidence of liver metastasis and a poor prognosis." (PMID 32093729, 2020). "The highest FLI1-expressing gastric cancer cell line, FU97, is an unusual variant of gastric cancer, showing alpha-fetoprotein production." (PMID 31231464, 2019). "Elevated AFP level was reported to be associated with liver metastasis and poor prognosis of gastric cancer." (PMID 29121872, 2017). "Elevated serum AFP has also been associated with a poor prognosis in gastric cancer, and it can predict liver metastasis after radical resection." (PMID 27533455, 2016). "A case report of an AFP-producing hepatoid gastric cancer associated with multiple liver metastases that was successfully treated with paclitaxel-based chemotherapy has recently been published." (PMID 20062620, 2009). "Hepatoid gastric adenocarcinoma is a distinct variant of gastric carcinoma which represents a comparatively small percentage of the disease and in many cases is producing high serum alpha-fetoprotein (AFP)." (PMID 20062620, 2009).
gastric cancer (continued). "AFP-producing gastric cancer is known to frequently cause multiple liver metastases and to have an extremely poor prognosis." (PMID 17634124, 2007). "We also believe that our protocol is an effective and safe treatment for liver metastases associated with AFP-producing gastric cancer." (PMID 17634124, 2007). "Alpha-fetoprotein (AFP)-producing gastric cancer is known to frequently cause multiple liver metastases and to have an extremely poor prognosis." (PMID 17634124, 2007). "We posit that the weak association of CA125 and AFP with the prognosis of gastric cancer patients may stem from their roles as indicators of peritoneal metastasis rather than as direct causal factors." (PMID 40406247, 2025). "Elevated AFP in gastric cancer may be associated with tumor cells exhibiting hepatoid differentiation, a subtype typically characterized by heightened invasiveness and a higher propensity for hepatic metastasis." (PMID 40406247, 2025). "In recent years, AFP’s potential diagnostic and prognostic utility in gastric cancer has garnered increasing attention, particularly within subtypes such as gastric hepatoid adenocarcinoma (GHA), where elevated levels are significantly correlated with tumor development, progression, and prognosis." (PMID 40485723, 2025). "AFP is closely associated with SALL4 expression in gastric carcinoma (both, P<0.0001)." (PMID 38817451, 2024). "Curiously, a small subset of carcinomas of the stomach and lung is also associated with elevated serum AFP levels and these relatively rare carcinomas exhibit histomorphological resemblance to hepatocellular carcinoma or immature endoderm-derived structures, such as the fetal gut or fetal lung." (PMID 34977100, 2021). "Gastric cancer is one of the most common cancers, and its AFP-positive variant has been reported to be characterized by a high proliferative activity, weak apoptosis, and rich neovascularization in comparison to AFP-negative gastric cancers." (PMID 32093729, 2020). "The potential underlying molecular mechanism of AFP-producing gastric cancer may be the common embryonic origin of the stomach and liver from the foregut." (PMID 29434637, 2017). "A PVTT is extremely rare in gastric cancer and has been reported to be associated with AFP-GC." (PMID 25591731, 2015). "Approximately 2 to 6% of gastric cancers produce AFP, and these are generally associated with high rates of venous invasion, lymph node metastasis and liver metastasis, and an extremely poor survival rate, compared with other gastric cancers." (PMID 22559879, 2012). "Indeed, AFP-producing gastric cancer is associated with a high incidence of multiple liver metastases, which render resection impossible." (PMID 17634124, 2007). "Our study exhibited a consistent finding on non-AFP-GC patients, which is a significant association between blood type A and gastric cancer." (PMID 29254216, 2017). "Although AFP production is rare in Gastric cancer, it has reported, and cases that exhibit pathological findings similar to YST are sometimes referred to as YST-like carcinomas." (PMID 41589237, 2026). "Alpha‐fetoprotein‐producing gastric cancer (AFPGC) is a rare histological subtype of gastric cancer that is often diagnosed at an advanced stage." (PMID 41190289, 2026). "Alpha-fetoprotein-producing gastric cancer (AFPGC) is a highly malignant subtype of gastric cancer with unique biological characteristics and clinical phenotypes." (PMID 42088224, 2026). "Summary of the previously reported cases of intramucosal alpha‐fetoprotein‐producing gastric cancer (AFPGC)." (PMID 41190289, 2026). "Mechanistically, AFP facilitates the migration and invasion of gastric cancer cells, potentially by upregulating the expression of metastasis-associated in colon cancer 1 (MACC1)." (PMID 40430002, 2025).
gastric cancer (continued). "This study seeks to retrospectively analyze the clinical and pathological characteristics of AFP-positive gastric cancer patients and investigate the relationship between AFP levels and clinical outcomes." (PMID 40485723, 2025). "Since HAS shares similar clinical and pathological features with AFP-producing gastric cancer, and prior reports have suggested the favorable efficacy of PD-1 blockade in HAS, this study aimed to evaluate the response of HAS to immunotherapy." (PMID 40999892, 2025). "This resulted in normalized AFP levels without recurrence for 1 year and 11 months post-treatment.This treatment regimen can also be combined with systemic chemotherapy to manage AFP-producing gastric cancers." (PMID 40538847, 2025). "Alpha‐fetoprotein‐producing gastric cancer (AFPGC), a rare and aggressive subtype of gastric cancer, presents a high risk of liver metastasis." (PMID 40433893, 2025). "Our study demonstrates AFP’s strong prognostic value in gastric cancer, particularly regarding metastatic propensity." (PMID 40485723, 2025). "As a result, despite preliminary research efforts, the absence of comprehensive prognostic models constrains the effective clinical application of AFP as a biomarker in gastric cancer." (PMID 40485723, 2025). "Our findings reveal a correlation between AFP-positive gastric cancer (AFPGC) and more aggressive disease characteristics, coupled with significantly worse OS." (PMID 40485723, 2025). "The results indicated that TNM staging, peritoneal metastasis, and CEA levels were significant prognostic factors for gastric cancer, whereas the independent associations of CA125 and AFP with survival were attenuated." (PMID 40406247, 2025). "Given the significant prognostic factors identified through multivariate analysis, a nomogram was crafted to predict 1-year, 3-year, and 5-year OS probabilities for AFP-positive gastric cancer patients." (PMID 40485723, 2025). "This study provides substantial evidence supporting the prognostic value of AFP in gastric cancer, particularly for patients who are AFP-positive." (PMID 40485723, 2025). "Our study also devised a nomogram to predict survival in AFP-positive gastric cancer patients, incorporating AFP levels along with T-stage, N-stage, and distant metastasis presence." (PMID 40485723, 2025). "While the precise role of AFP in gastric cancer is still under investigation, current evidence suggests it influences tumor growth, immune evasion, and metastasis, similar to its known function in HCC." (PMID 40430002, 2025). "Biological aggressiveness of alpha-fetoprotein (AFP)-positive gastric cancer The prognostic implications of elevated AFP levels are considerable." (PMID 40485723, 2025). "Alpha‐fetoprotein‐producing gastric cancer (AFPGC) is a rare but highly aggressive subtype of gastric cancer." (PMID 40433893, 2025). "presented a case study involving a patient with multiple liver metastases from gastric cancer exhibiting significantly elevated AFP levels (588.9 ng/mL)." (PMID 40538847, 2025). "While numerous studies underscore the potential of AFP in the context of gastric cancer, existing literature predominantly focuses on its correlation with specific clinical and pathological features." (PMID 40485723, 2025). "AFP-producing gastric cancer is considered a highly aggressive subtype, characterized by a high frequency of early liver and lymph node metastases." (PMID 40430002, 2025). "In recent years, AFP was recently recognized as an independent prognostic factor for poor outcomes of gastric cancer, particularly in AFP-producing gastric cancer." (PMID 40900791, 2025). "In clinical practice, AFP-producing carcinoma (AFPGC) is often defined as gastric cancer with a serum AFP level >20 ng/ml or immunohistochemical evidence of AFP positivity." (PMID 41561743, 2025). "High AFP levels in gastric cancer often correlate with a poorer prognosis, larger tumor size, and increased risk of metastasis." (PMID 40430002, 2025).